GSTP1 (glutathione S-transferase pi 1)
Diseases named in the same sentence as GSTP1 in open-access papers (continued):
Sharing a sentence is not in itself a finding about the gene and the disease.
heart failure (7 papers, 2020 to 2025). Inability of the heart to pump blood at an adequate rate to meet tissue metabolic requirements. "In patients with heart failure, increased GSTP1 expression is associated with a cellular response to oxidative stress and inflammation." (PMID 35626917, 2022). "It has been reported that the variant of the GSTP1-Val genotype might contribute to declined antioxidant activity in patients with heart failure and cardiovascular diseases." (PMID 36674274, 2023). "GSTP1 is a more specific predictor of left ventricular function in patients with heart failure compared to N-terminal pro-B-type natriuretic peptide (NT-proBNP)." (PMID 35626917, 2022). "Previous studies have shown that extracellular GSTP1 can cross plasma membrane, and rGSTP1 protects against infarction-induced heart failure and LPS-induced acute lung injury by reducing infarct area, apoptosis, and inflammation." (PMID 31515511, 2020). "These miRNAs also target the glutathione transferase P1 (GSTP1), an enzyme involved in detoxification and a potential biomarker of myocardial stress and heart failure, and the hyperpolarization-activated cyclic nucleotide-gated 4 (HCN4) channel, a transmembrane protein which regulates heart rate." (PMID 39684483, 2024). "The glutathione-S-Transferase pi 1 (GSTP1) gene is highly polymorphic and involved in many diseases including cancer and heart failure." (PMID 34859074, 2021).
liver diseases (7 papers, 2012 to 2025). "Nowadays, the studies about molecular biology and GSTP1 gene polymorphisms in many different human pathologies (e.g., tumors, autoimmune, neurodegenerative and liver diseases) represent only the beginning of a conceivable use of GSTP1 as a clinical marker in biomedicine." (PMID 31357662, 2019). "In addition, decreased GSTP1 and CYP1A1 expression induced by methylation of the GSTP1 and CYP1A1 promoters, respectively, has been reported in many liver diseases such as acute-on-chronic hepatitis B liver failure." (PMID 25798582, 2015).
lymph node metastasis (7 papers, 2006 to 2022). "Methylation of RASSF1 (P= 0.012) and GSTP1 (P=0.028) were associated with lymph node metastasis." (PMID 27065772, 2016). "In this study, GSTP1 methylation exhibited a trend toward relationship with lymph node metastasis and increasing IDC grade." (PMID 27065772, 2016). "The AORs with their 95% CIs of GSTP1 and GSTA1 gene polymorphisms on the clinico-pathological characteristics, such as clinical stage, tumor size, lymph node metastasis, distant metastasis, and Child-Pugh grade in HCC patients were also estimated." (PMID 20331903, 2010). "Comparing the lymph node metastasis to the matched normal tissue, the former revealed differentially lower methylation ratio for BIN1, GSTP1 and P14 promoter regions (P < 0.05, P < 0.01, P < 0.05; respectively)." (PMID 22695536, 2012). "Methylation of GSTP1 (P=0.028) and RASSF1 (P=0.012) were related with lymph node metastasis." (PMID 27065772, 2016). "GSTP1 hypermethylation was more frequent in the lymph node metastasis positive group than in the negative group." (PMID 18485221, 2008).
squamous cell carcinoma (7 papers, 2007 to 2025). A carcinoma arising from squamous epithelial cells. "In human squamous cell carcinoma, pathological observations indicated a strong connection between higher GSTP1 nuclear staining and shorter survival." (PMID 34209254, 2021). "Moreover, in samples from clinical squamous cell cancer, six genes (GAL, GSTP1, MRPL11, MRPL21, SF3B2, and YIF1A) at 11q13.1–13.3 and one gene (GALR1) at 18q23 showed significant differences in expression between normal and tumor samples." (PMID 31552180, 2019).
chronic myeloid leukemia (6 papers, 2014 to 2022). "The aim of the present study is to investigate the association of GSTP1, GSTM1 and GSTT1 gene polymorphisms in susceptibility to Chronic Myeloid Leukaemia (CML)." (PMID 32102530, 2020).
Cirrhosis (6 papers, 2012 to 2025). A chronic disorder of the liver in which liver tissue becomes scarred and is partially replaced by regenerative nodules and fibrotic tissue resulting in loss of liver function. "As a diagnostic marker, GSTP1 methylation can obviously enhance the risk of HBV-associated HCC patients with cirrhosis." (PMID 34660653, 2021). "One good example of ctDNA monitoring is a study which analyzed hypermethylation of the GSTP1 promoter hypermethylation in healthy individuals and patients with cirrhosis and HCC." (PMID 31608239, 2019). "High levels of methylation of the specific region (5' of−48) of the GSTP1 promoter are more abundant in HCC (37%), compared to other liver conditions including hepatitis, cirrhosis, as well as healthy control (all 0%), and only 15% of HCC cases show no methylation." (PMID 31608239, 2019). "To test this hypothesis, we compared the methylation status of the GSTP1 promoter region of the DNA isolated from HCC, cirrhosis, hepatitis, and normal liver tissues by bisulfite–PCR sequencing." (PMID 22536438, 2012). "When we used an assay targeting the 3′ region, we found that the methylation of the 5′-end of the GSTP1 promoter was significantly more specific than that of the 3′-end (97.1% vs. 60%, p<0.0001 by Fisher's exact test) for distinguishing HCC (n = 120) from hepatitis (n = 35) and cirrhosis (n = 35)." (PMID 22536438, 2012).
glaucoma (6 papers, 2011 to 2023). Increased pressure in the eyeball due to obstruction of the outflow of aqueous humor. "Yang and colleagues (2001) reported serum autoantibodies against glutathione S-transferase in glaucoma, whereby the P variant (Gene name: GSTP1) was specifically detected in RET samples in the present work." (PMID 31470587, 2019). "In summary, the present meta-analysis suggested that combination of GSTM1 and GSTT1 null genotypes, and GSTM1 null and GSTP1 105-Val allele genotypes are associated with increased risk for glaucoma in Caucasian populations." (PMID 23342067, 2013). "Since the studies included were very limited, it is necessary to validate the association between GSTP1 Ile 105 Val polymorphism and glaucoma risk in future studies." (PMID 23342067, 2013). "The combination of GSTM1 null and GSTT1 null, or GSTM1 null and GSTP1 genotype was associated with increased risk of glaucoma." (PMID 23342067, 2013). "All studies evaluating the association between GSTM1, GSTT1 and GSTP1 polymorphisms and glaucoma risk were included." (PMID 23342067, 2013). "Due to the limited studies, we did not perform meta-analysis for association between the combined GSTM1 null, GSTT1 null and GSTP1 105-Val allele genotypes and glaucoma risk." (PMID 23342067, 2013). "Our meta-analysis results showed that the association between combined of GSTM1 and GSTT1 null genotypes, or GSTM1 null and GSTP1 Val genotypes, and the risk for glaucoma is statistically significant in Caucasians." (PMID 23342067, 2013). "In this study, we have conducted a meta-analysis to assess the association between polymorphisms of GSTM1, GSTT1 and GSTP1 and glaucoma risk." (PMID 23342067, 2013). "Meta-analysis of the GSTP1 Ile105Val polymorphism on glaucoma risk." (PMID 23342067, 2013). "GSTP1, a redox‐related protein, is expected to become a target for preventing the onset of or treating glaucoma." (PMID 33599104, 2021). "For the glaucoma type, this meta-analysis included ten, eight, and three studies on the relationship between GSTM1, GSTT1, and GSTP1 polymorphism and risk of POAG (the most common form of glaucoma), respectively." (PMID 23342067, 2013). "We also examined the association between GSTP1 Ile 105 Val polymorphism and glaucoma risk, and the overall result showed that GSTP1 polymorphism was not correlated with glaucoma risk in all four models by pooling all four studies." (PMID 23342067, 2013). "Interestingly, increased glaucoma risk was associated with the combined GSTM1 and GSTT1 null genotypes (OR, 2.20; 95% CI, 1.47–3.31), and with the combined GSTM1 null and GSTP1 Val genotypes (OR, 1.86; 95% CI, 1.15–3.01)." (PMID 23342067, 2013). "For glaucoma, PTGDS, GSTP1, SPD1, and CST3 were expressed significantly higher in almost all tissues; CRP, ALB, and TTR were markedly increased in the liver; MBP and TF exhibited high expression in the brain." (PMID 37052519, 2023).
invasive breast carcinoma (6 papers, 2010 to 2017). A carcinoma that infiltrates the breast parenchyma. "Hypermethylation of RASSF1 was most frequent, present in 14/17 cases, followed by APC in 12/17, and GSTP1 in 9/17 cases with establishment of an epigenetic monocloncal progression continuum to invasive breast cancer." (PMID 21776373, 2011). "Recently, it has been shown that the absence of GSTP1 protein expression correlate with promoter hypermethylation and with improved survival in invasive breast cancer samples." (PMID 24093668, 2013). "The observed improved survival has very recently been shown in samples in concordance with previous reports where the absence of GSTP1 protein expression correlated with improved survival in invasive breast cancer samples." (PMID 20338046, 2010).
lung adenocarcinoma (6 papers, 2013 to 2023). A carcinoma that arises from the lung and is characterized by the presence of malignant glandular epithelial cells. "We also show the clinical relevance of these findings and establish GSTP1 as a poor diagnostic and prognostic marker, as well as a therapeutic target for human lung adenocarcinoma." (PMID 31263672, 2019). "Fifth, GSTP1 expression is a poor diagnostic and prognostic marker for human lung adenocarcinoma, thus is of high clinical relevance." (PMID 31263672, 2019). "GSTP1 expression is a poor diagnostic and prognostic marker for human lung adenocarcinoma thus is of high clinical relevance." (PMID 31263672, 2019). "Moreover, we show that GSTP1 expression is a poor diagnostic and prognostic marker for human lung adenocarcinoma, thus is of high clinical relevance." (PMID 31263672, 2019). "However, whether GSTP1 supports cancer stem cells (CSCs) and the underlying mechanisms in lung adenocarcinoma (LUAD) remain largely unknown." (PMID 36709476, 2023). "GSTP1 inhibitor Ezastiostat exhibits the potential as a combined treatment with tyrosine kinase inhibitor (TKI) to reverse TKI resistance, illustrating GSTP1 as promising therapeutic target for lung adenocarcinoma." (PMID 36709476, 2023). "The differential GSTP1 expression between the cancer tissue and the normal lung was drastic and the elevation in lung adenocarcinoma tissues was profound." (PMID 31263672, 2019). "High GSTP1 mRNA levels are correlated with faster disease progression and a lower rate of survival in lung adenocarcinoma." (PMID 31263672, 2019). "We analyzed GSTP1 mRNA expression in this clinical cohort and found higher GSTP1 expression in advanced lung adenocarcinoma compared to that in early stage lung adenocarcinoma." (PMID 31263672, 2019). "We also found that high GSTP1 mRNA levels are correlated with faster disease progression and a lower rate of survival in lung adenocarcinoma." (PMID 31263672, 2019). "We next analyzed the prognostic value of GSTP1 expression by examining the relationship between GSTP1 expression and lung adenocarcinoma progression using the publicly accessible TCGA (analyzed in Oncolnc website) and Kaplan-Meier Plotter (analyzed in Kaplan-Meier Plotter website) databases." (PMID 31263672, 2019).
metastatic disease (6 papers, 2012 to 2024). "Messenger RNA of the GSTP1 gene has been previously shown to be significantly down-regulated in primary PCa, and metastatic tumors show further down-regulation." (PMID 23119026, 2012). "Notably, we found that proteins involved in triple‐negative breast cancer (TNBC), such as GSTP1 and EPCAM, were enriched in ERα‐N metastatic tumours, while proteins typically upregulated in ERα‐P disease, such as ALCAM and KRT18, were enriched in ERα‐P as well as the ERα‐C metastatic tumours." (PMID 37854018, 2024).
neutropenia (6 papers, 2012 to 2025). A decrease in the number of neutrophils found in the blood. "In the bivariate analysis, the AA genotype (AA vs. G) of the GSTP1 rs1695 polymorphism was found to be associated with severe overall toxicity (p = 0.03; OR = 2.55; 95% CI = 1.02–6.70) and neutropenia (grades I–IV) (p = 0.02; OR = 2.64; 95% CI = 1.11–6.50)." (PMID 40430876, 2025). "The logistic regression analysis indicated that GSTP1 c.313A > G mutation (A/G + G/G vs. A/A genotype) (adjusted OR 4.273, 95% CI 1.141–16.000, P = 0.031) was an independent variable associated with neutropenia." (PMID 35729577, 2022). "In a North American population, patients with the GSTP1 c.313A > G A/A genotype had a lower incidence of grade III and IV neutropenia than those with the GSTP1 c.313A > G G allele." (PMID 35729577, 2022). "For example, in the case of patients with the variant GSTP1 genotype, should stimulating factors be considered as a strategy to minimize their risk of neutropenia?" (PMID 23346096, 2012). "For example, should patients with the homozygous variant GSTP1 genotype receive lower doses as an attempt to reduce their risk of severe neutropenia, and therefore avoid treatment delays or interruption that could compromise the final response outcomes?" (PMID 23346096, 2012). "The results indicated that GSTP1 c.313A > G mutation (A/G + G/G vs. A/A genotype) (age-, menopause-, T-stage, N-stage, clinical stage-, molecular subtype-, and chemotherapy regimen/dose-adjusted OR 4.273, 95% CI 1.141–16.000, P = 0.031) was an independent variable associated with neutropenia." (PMID 35729577, 2022). "Here, we evaluated additional SNPs on the candidate genes: CYP3A4*22, GSTP1, ERCC2, SLCO1B1, and ABCG2, but did not observe a significant relationship with neutropenia and neurotoxicity except for XRCC3 316A>G rs1799794 for GG+AG alleles (p = 0.03)." (PMID 29163177, 2017).
acute leukemia (5 papers, 2013 to 2025). A clonal (malignant) hematopoietic disorder with an acute onset, affecting the bone marrow and the peripheral blood. "This study, performed using samples derived from Argentine patients with Acute Leukemia, revealed that a variant allele of GSTP1 increased the risk of childhood ALL relapse and shortened the RFS." (PMID 27058755, 2017). "The pooled OR of acute leukemia risks associated with GSTM1 null genotype, GSTP1 Val105 allele and GSTT1 null genotype, were 1.22 (95% CI 1.07–1.38), 1.07 (95% CI 1.00–1.13) and 1.19 (95% CI 1.00–1.41), respectively." (PMID 28902850, 2017). "A systematic review with meta-analysis was performed to investigate the association between GST polymorphisms (GSTM1, GSTP1 and GSTT1) and the development of acute leukemia, since the overall results of existing published studies remained inconsistent with each other." (PMID 28902850, 2017).
acute myeloid leukemia (5 papers, 2016 to 2024). Acute myeloid leukemia (AML) is a group of neoplasms arising from precursor cells committed to the myeloid cell-line differentiation. "The purpose of the study was to evaluate the association between CAT C262T, GPX1 Pro198Leu, MnSOD Ala16Val, GSTM1, GSTT1, and GSTP1 Ile105Val gene polymorphisms and acute myeloid leukemia risk, in a case-control study comprising 102 patients and 303 controls." (PMID 26823947, 2016). "In a meta-analysis, it was revealed that, the GSTM1-null genotype, but not GSTP1 Ile105Val polymorphism, was associated with an increased risk of acute myeloid leukemia in East Asians and GSTT1-null genotype in Caucasians." (PMID 29204680, 2018).
adenoma (5 papers, 2005 to 2021). A neoplasm arising from the epithelium. "A genetic score comprising genes encoding for SOD2 (eight SNPs), CAT (11 SNPs) and GSTP1 (five SNPs), following an additive model of inheritance (0, 1 and 2 points awarded for every high-risk allele) or a SNP—adenoma risk-specific score, was explored for this purpose." (PMID 30987200, 2019). "The ratio (Q2) was also associated with an increased risk of high-risk and low-risk adenomas in individuals with the GSTM1 common allele and the GSTP1 codon 105 variant allele (Val allele)." (PMID 18093316, 2007). "In contrast, our method is based on the difference in GSTP1-1 expression between ACF cells and normal epithelial cells: Normal colorectal epithelial cells express a very low level of GSTP1-1; however, GSTP1-1 is expressed in ACF, adenomas, and subsequent CRCs." (PMID 28747791, 2017). "In addition we found weak evidence of a modifying effect by the GSTP1 and GSTM1 genotypes on the ratio of total meat to total fruit, berry and vegetable intake in adenomas." (PMID 18093316, 2007).
Alzheimer disease (5 papers, 2019 to 2025). A progressive, neurodegenerative disease characterized by loss of function and death of nerve cells in several areas of the brain leading to loss of cognitive function such as memory and language. "It has been found that the Hub gene GSTP1 of the sixth module is considered to be a risk factor for Alzheimer's disease." (PMID 34992508, 2021). "For instance, the GSTP1 Ile105Val polymorphism and GSTM1 null genotype but not the GSTT1 null genotype seem to increase the risk of Alzheimer’s disease." (PMID 30617052, 2019).
anemia (5 papers, 2018 to 2024). A reduction in the number of red blood cells, the amount of hemoglobin, and/or the volume of packed red blood cells. "In conclusion, the present study suggests that GSTP1 c.313A>G is a potential predictor of anemia and thrombocytopenia and associated with a lower risk of dose delay during chemotherapy." (PMID 33326171, 2021). "The GSTP1 c.313A>G AG genotype was associated with reduced risk of anemia (OR: 0.15, 95% CI: 0.03–0.82, P = 0.03)." (PMID 33326171, 2021). "The GSTP1 c.313A>G (dominant model: AA + AG vs. GG) was associated with reduced risk of anemia and thrombocytopenia." (PMID 33326171, 2021). "Previous studies have demonstrated the association between chemotherapy‐related severe anemia and thrombocytopenia and the GSTP1 c.313A>G polymorphism in patients who received carboplatin and paclitaxel‐based chemotherapy." (PMID 33326171, 2021). "Tulsyan and coworkers focused on three GST members, GSTM1, GSTP1, and GSTT1, and found one significant association between GSTP1 rs1695 and grade ≥2 anemia." (PMID 32351390, 2020). "The other positive findings which found in our study was the association between GSTP1 polymorphism (A>G, rs1695) and more severe anemia which consistent with Korean and Japanese studies." (PMID 32711417, 2020). "ERCC1 polymorphism were associated with platinum resistance, while GSTP1 polymorphism was associated with grade 2 of anemia." (PMID 32711417, 2020). "In addition, the significant association of GSTP1 polymorphism and grade 2 anemia was found." (PMID 32711417, 2020). "Severe anemia was found in 13 (11.6%) women and GSTP1 c.313A>G AG genotype were less likely to have severe anemia (P = 0.04); only 23% of women with severe anemia in GSTP1 c.313A>G (dominant model: AA vs. AG + GG) compared with 60% of subjects with no toxicity." (PMID 33326171, 2021). "Patients with A/G genotype of GSTP1 had higher rate of grade 2 anemia (81.8% vs 46.3%, p =0.036)." (PMID 32711417, 2020).